THRSP (thyroid hormone responsive)
Description:
Plays a role in the regulation of lipogenesis, especially in lactating mammary gland. Important for the biosynthesis of triglycerides with medium-length fatty acid chains. May modulate lipogenesis by interacting with MID1IP1 and preventing its interaction with ACACA (By similarity). May function as transcriptional coactivator. May modulate the transcription factor activity of THRB.
Synonyms: S14; SPOT14; Lpgp; THRP; LPGP1
Tractability: No criterion of Open Targets' tractability assessment is met for any kind of drug.
Gene: Protein-coding gene on chromosome 11 (78,063,861 to 78,068,351, forward strand). Ensembl gene ENSG00000151365.
Subcellular location: Nucleus; Cytoplasm
Subcellular location (Human Protein Atlas): Nucleoplasm
Pathways (Reactome):
Gene expression (Transcription): MLL4 and MLL3 complexes regulate expression of PPARG target genes in adipogenesis and hepatic steatosis
Metabolism: Carnitine shuttle
Gene Ontology:
Molecular function: identical protein binding; protein binding; molecular function activator activity; molecular function inhibitor activity; protein homodimerization activity
Biological process: carnitine shuttle; lipid metabolic process; regulation of lipid biosynthetic process; regulation of triglyceride biosynthetic process
Cellular component: cytosol; nucleus; cytoplasm
Genetic constraint (gnomAD): Loss-of-function variants: 9 observed, 11.22 expected, observed/expected ratio (o/e) 0.8, 90% interval 0.48 to 1.4. The upper end of that interval is the gene's LOEUF score, 1.4, which puts it in group 5 of 6, group 1 being the genes least tolerant of losing a copy. Missense variants: 177 observed, 198.09 expected, observed/expected ratio (o/e) 0.89, 90% interval 0.79 to 1.01. Synonymous variants: 73 observed, 82.8 expected, observed/expected ratio (o/e) 0.88, 90% interval 0.73 to 1.07.
Homologues: Orthologues: chimpanzee THRSP (99% identical), macaque THRSP (92% identical), rabbit THRSP (90% identical), mouse Thrsp (85% identical), rat Thrsp (83% identical), pig THRSP (77% identical), dog THRSP (74% identical), guinea pig THRSP (74% identical), zebrafish thrsp (30% identical), Drosophila melanogaster CG2765 (22% identical). Paralogues in human: MID1IP1 (36% identical).